SOX10 (SRY-box transcription factor 10)
Diseases named in the same sentence as SOX10 in open-access papers (continued):
Sharing a sentence is not in itself a finding about the gene and the disease.
synovial sarcoma (3 papers, 2013 to 2023). "Although of limited sensitivity, a positive SOX10 result strongly supports a diagnosis of MPNST over synovial sarcoma, and with its other diagnostic applications for neuropathology this is a practical and accessible tool for neuropathologists to employ." (PMID 24131748, 2013). "SOX10 staining revealed a 67% positivity rate in MPNST cells compared to only 7% in synovial sarcomas." (PMID 38132479, 2023). "Forty-eight cases of MPNST and 97 cases of synovial sarcoma, including four intraneural synovial sarcomas, were stained for SOX10." (PMID 38132479, 2023). "Synovial sarcomas, desmoid fibromatosis, and glomus tumors showed fewer than 5% of SOX10-positive nuclei, possibly representing entangled neural components." (PMID 38132479, 2023). "SOX10 and S100 mRNA levels were evaluated in 122 cases of peripheral nerve sheath tumors and synovial sarcomas, and IHC was used for SOX10 and S100 protein expression in 1012 tissue specimens." (PMID 38132479, 2023). "Sixty-seven percent of MPNST (32/48) and only 7% (7/97) of synovial sarcomas were positive for SOX10." (PMID 38132479, 2023). "Nevertheless, there is uncertainty as to whether SOX10-positive cells in intraneural synovial sarcoma represent entangled Schwann cells, synovial sarcoma cells, or both." (PMID 38132479, 2023). "We caution readers that in truly intra-neural synovial sarcomas the entrapped nerve elements may label with SOX10." (PMID 24131748, 2013). "Whether SOX10-positive cells in intraneural SS represent entrapped Schwann cells, synovial sarcoma cells, or both, remains to be determined." (PMID 33076385, 2020). "Half of the monophasic synovial sarcomas expressed CK7, CK19 or panCK in a “rare positive cells pattern”, 8/9 (89%) expressed EMA, and all were SOX10 immunonegative with reduced but variable BAF47 expression." (PMID 24131748, 2013). "Synovial sarcomas expressed significantly higher levels of S100 than SOX10, and no significant SOX10 mRNA expression was identified in synovial sarcoma." (PMID 38132479, 2023). "All 79 of Karamchandani’s synovial sarcomas were negative for SOX10 immunohistochemistry, and the 15 synovial sarcomas studied by Nonaka were negative for SOX10." (PMID 24131748, 2013). "One of our synovial sarcoma mimics was SOX10 negative, and as this case also had CK expression (Case 16, a malignant SFT) it was reasonable to pursue SYT-SSX testing to rule out synovial sarcoma." (PMID 24131748, 2013). "The 3 “synovial sarcoma mimics” were either CK negative or diffusely CK positive and none had the “scattered positive cells” pattern, two had some S100 expression, one had focal SOX10 immunolabeling." (PMID 24131748, 2013). "Two MPNST were SOX10 negative (including Case 11 (an epithelioid MPNST) and Case 15 (the possibility of synovial sarcoma was ruled out on genetic testing for SYT-SSX)) (67% sensitivity overall)." (PMID 24131748, 2013).
amelanotic malignant melanoma (2 papers, 2022 to 2024). "Although Sox10 has not been confirmed as a marker for feline melanocytic tumors, it is expected to be positive as well, raising the doubt of a spindle amelanotic melanoma as a differential diagnosis in our cases." (PMID 38612342, 2024).
astrocytic tumor (2 papers, 2024 to 2025). A glial tumor of the brain or spinal cord showing astrocytic differentiation. "This aberrant discrepancy was also observed in Olig2-CKO and dCKO tdTOM+ astrocytic tumors, in which about 10% of tumor cells are SOX10+." (PMID 39609428, 2024).
autism (2 papers, 2022). Persistent deficits in social interaction and communication and interaction as well as a markedly restricted repertoire of activity and interest as well as repetitive patterns of behavior. "Reduced expression of SOX10, a transcription factor, was observed in the limbic system including the hippocampus, retrosplenial cortex, and para hippocampal gyrus of mice related to autism." (PMID 36817099, 2022).
cervical carcinoma (2 papers, 2017 to 2024). A carcinoma arising from either the exocervical squamous epithelium or the endocervical glandular epithelium. "In cervical mutation, HR-HPV 16 and HPV 18 are the main variants responsible as they hijack the LINE-1 Sox10 of host stem cells, which leads to hypomethylation and is crucial in cervical cancer progression." (PMID 38732382, 2024).
chordoma (2 papers, 2022 to 2025). Chordomas are rare malignant tumors arising from embryonic remnants of the notochord in axial skeleton. "AE1/AE3, S100, EMA, and CAM5.2 were consistent with chordomas, and the lack of staining for other markers such as SOX10, P63, and SMA excluded other neoplasms." (PMID 40631598, 2025). "Immunohistochemical analysis showed positive reactivity for AE1/AE3, S100, epithelial membrane antigen (EMA), CAM5.2, NSE, and Ki‐67 (< 1%) and negative reactivity for SOX10, P63, SMA, and calponin, which indicated tumors of a notochordal origin and confirmed the final diagnosis of chordoma." (PMID 40631598, 2025). "However, the tumor was finally diagnosed as chordoma based on positive staining for the expression of brachyury, SOX9, and EMA and negative staining for the expression of SOX10." (PMID 35398781, 2022).
Cirrhosis (2 papers, 2007 to 2022). A chronic disorder of the liver in which liver tissue becomes scarred and is partially replaced by regenerative nodules and fibrotic tissue resulting in loss of liver function. "Cirrhosis was present in two livers, one of which had the highest SOX10 tag methylation and high CSX tag methylation (Pt M)." (PMID 17672908, 2007). "Several oncogenic transcription factors (TFs) inferred with DoRothEA35 including FOS, ETS2, RELB, SOX10, ERG, WT1 and JUND and TFs supporting stemness such as PBPJ and ARID3A were upregulated in cirrhosis patients and correlated with bacterial translocation." (PMID 35803930, 2022).
cleft lip (2 papers, 2024). Congenital defect in the upper lip where the maxillary prominence fails to merge with the merged medial nasal prominences. "Eight significant variants associated with craniofacial malformations such as non-syndromic cleft lip and palate, mandibular prognathism, ocular abnormalities, and tooth defects are found in AXIN2, BMP2, BMP4, NOTCH3, PTCH1, SOX10, and WNT10A." (PMID 38785976, 2024).
desmoplastic melanoma (2 papers, 2023 to 2025). A melanoma of the skin characterized by a proliferation of atypical spindled melanocytes in the dermis, in a background of abundant collagen. "There are also reported cases of SOX10-negative desmoplastic melanomas." (PMID 40507250, 2025).
Down syndrome (2 papers, 2013 to 2017). "This does not come as a total surprise, as several known HSCR genes (e.g., KBP, SOX10, NRG1, IKBKAP, ZEB2, PHOX2B) are involved in both CNS and ENS pathologies and the fact that HSCR is strongly associated with Down syndrome." (PMID 28274275, 2017).
ear malformation (2 papers, 2018 to 2022). "Congenital inner ear malformations were more common, and semicircular malformations were exclusively observed in probands with SOX10 mutations." (PMID 36329483, 2022). "Although accumulating evidence has shown that SOX10 mutations can induce inner ear malformations in humans, the target genes and pathways regulated by SOX10 involved in the inner ear development remain to be fully investigated." (PMID 29922125, 2018).
ependymal neoplasms (2 papers, 2021 to 2024). "Our case was classified as a subependymoma because it did not express Olig2 and SOX10 markers, which are absent in ependymal tumors." (PMID 38581034, 2024). "Expression of particular markers differentially expressed in astrocytic and in ependymal neoplasms revealed low OLIG2 and SOX10 expression (adjusted p = 3.89e − 26 and adjusted p = 7.75e − 65) within the novel group, with similar expression of GFAP (online resource)." (PMID 34355256, 2021).
head and neck squamous cell carcinoma (2 papers, 2021 to 2024). A squamous cell carcinoma that arises from any of the following anatomic sites: lip and oral cavity, nasal cavity, paranasal sinuses, pharynx, larynx, and salivary glands. "The top-ranked somatic eQTL genes with truncations include OR8D1 in LUSC, SOX10 in head and neck squamous cell carcinoma (HNSC), and PSG7 in kidney renal clear cell carcinoma (KIRC)." (PMID 33691015, 2021).
ischemia (2 papers, 2024). A hypoperfusion of the BLOOD through an organ or tissue caused by a PATHOLOGIC CONSTRICTION or obstruction of its BLOOD VESSELS, or an absence of BLOOD CIRCULATION. "To investigate the sex-dependent differentiation of Sox10 cells and their response to pathological conditions such as lipopolysaccharide (LPS) exposure or ischemia, we utilized Sox10 Cre-ERT2, tdTomato mice." (PMID 39106252, 2024). "It has been reported that ischemia can induce a retraction of oligodendrocyte processes, decreasing their myelination capacity, and so we evaluated the effect of ischemia and agathisflavone on the morphology of SOX10-EGFP+ oligodendroglia." (PMID 39275007, 2024).
lymph node metastasis (2 papers, 2016 to 2021). "As SOX10 correlates with the rate of lymph node metastasis, a double positivity of MMs for SOX10/SOX11 might be used as an indicator of the presence of tumor cells in lymphatic and systemic circulation." (PMID 33801642, 2021). "In patient No. 3 a lymph node metastasis appeared during treatment with no increased SOX10 reactivity in serum." (PMID 27110718, 2016).
melanocytic neoplasm (2 papers, 2021 to 2022). "In addition, the lack of immunolabeling for SOX-10 can be used to exclude melanocytic origin, as the antibody had 100% sensitivity for detecting melanocytic neoplasms in that same study." (PMID 35448673, 2022). "However, positive labeling for SOX-10 does not distinguish between soft tissue sarcomas and melanocytic neoplasms, as the antibody labels a percentage of canine soft tissue sarcomas." (PMID 35448673, 2022). "The lack of immunoreactivity for SOX-10 may be useful to exclude a melanocytic neoplasm, but labeling for SOX-10 should not be used as a single criterion for confirmation of a diagnosis of OMM." (PMID 34422947, 2021).
melanoma in situ (2 papers, 2025). "Regarding differential diagnosis, MITF can be used to differentiate actinic keratosis with melanocyte hyperplasia from melanoma in situ with greater efficacy than SOX10." (PMID 40507250, 2025).
mental disorder (2 papers, 2014 to 2019). A disease that has its basis in the disruption of mental process. "Therefore our finding that DISC1, a key psychiatric disease susceptibility gene, controls Sox10 and/or Nkx2.2 expression is intriguing." (PMID 24516667, 2014). "Overall, our findings suggest that DISC1 dysfunction may cause impaired differentiation of oligodendrocytes by affecting Sox10 and/or Nkx2.2 expression, and consequently contribute to the pathophysiology of psychiatric disorders." (PMID 24516667, 2014).
metaplastic breast carcinoma (2 papers, 2022 to 2025). A group of invasive breast carcinomas characterized by the presence of an adenocarcinomatous component which is admixed with a dominant component that is composed of squamous cells, spindle cells, or mesenchymal cells. "Concordant with these findings, we noted a considerably higher positivity for TRPS1 in metaplastic breast carcinoma (100%) compared with GATA3 (42.9%) and SOX10 (66.7%)." (PMID 40025593, 2025). "TNBCs and metaplastic breast carcinoma, showed higher positivity of TRPS1, compared with GATA3 and SOX10." (PMID 40025593, 2025).
metastatic carcinoma (2 papers, 2015 to 2021). A carcinoma which has spread from the original site of growth to another anatomic site. "SOX10, in turn, remains the most stable when comparing the expression between primary and metastatic carcinoma, and in addition, it is capable of allowing the detection of cases in which there is no expression of GATA3." (PMID 34771579, 2021). "SOX10, androgen receptor, and GATA3 expression studies have recently been carried out in TNBC, both in primary tumors and in metastatic carcinomas." (PMID 34771579, 2021). "SOX-10 can potentially differentiate choroidal melanoma from metastatic carcinomas, since it has been proven to be negative in epithelial carcinomas." (PMID 26316887, 2015).
Mondini dysplasia (2 papers, 2017 to 2018). "As examples, the mutation of SOX10 (R109W) in pig causes inner ear malfunctions and mimics human Mondini dysplasia, and upregulated expression of FBXO32 is associated with congenital splay legs." (PMID 28639938, 2017). "SOX10 may be responsible for human Mondini dysplasia, and this strain represents the first inherited animal model for this disease." (PMID 29922125, 2018).
ovarian carcinoma (2 papers, 2023). A malignant neoplasm originating from the surface ovarian epithelium. "While SOX10’s involvement in ovarian carcinomas was assessed, other common expression markers studied for ovarian cancer include SOX8 and, notably, SOX9, which has been implicated in various signaling pathways in ovarian cancer development." (PMID 38132479, 2023). "Particularly in ovarian cancer, SOX10’s involvement in chemoresistance highlights its significance in clinical settings." (PMID 38132479, 2023). "Conversely, concerning ovarian cancers, distinguishing between SOX10 expression within the nucleus and cytoplasm has shown promise in estimating grade and prognosis." (PMID 38132479, 2023). "In the ovarian cancer tissues, further significant positive correlations were observed between DAB2 and CSC markers (CD34, ALDH1A1, CD117 (Kit)) and mesenchymal markers (MMP9, SNAI1 and MMP3) and negative correlations with mesenchymal markers (CDH2, FOXC2 and SOX10)." (PMID 37815603, 2023).
pilocytic astrocytoma (2 papers, 2013 to 2022). Pilocytic astrocytoma is a rare subtype of low-grade glioma of the central nervous system characterized by a well circumscribed, often cystic, brain tumor with a discrete mural nodule and long, hair-like projections that extend from the neoplastic astrocytes. "Furthermore, pilocytic astrocytomas are generally diffusely positive for OLIG2 and SOX10, whereas in this case OLIG2 and SOX10 expression was seen in only a subset of cells." (PMID 35484611, 2022).
retinoblastoma (2 papers, 2015 to 2017). A malignant tumor that originates in the nuclear layer of the retina. "We have also been able to demonstrate diffuse SOX-10 nuclear positivity in a case of retinoblastoma." (PMID 26316887, 2015). "The observation of distinct, diffuse nuclear SOX-10 expression in retinal inner and outer nuclear layers is a finding that warrants further investigation as a marker for retinoblastoma." (PMID 26316887, 2015).
acral melanoma (1 paper, 2025). "Particularly in acral melanoma (AM), little were known for SOX6 in promoting AM progression, compared to other SOX family members like SOX4 and SOX10." (PMID 40866912, 2025).
acute appendicitis (1 paper, 2022). "We present a unique case of an Aboriginal Australian adult with acute appendicitis and concurrent ganglioneuroma diagnosed using histopathology and immunohistochemistry using Neu-N, S100 and Sox-10." (PMID 35079345, 2022).
adenosis (1 paper, 2024). "Carcinoma arising in the context of microglandular adenosis demonstrated diffuse strong positivity for SOX10 and variable expression of S100." (PMID 37306115, 2024).
adenosquamous carcinoma (1 paper, 2018). A carcinoma composed of malignant glandular cells and malignant squamous cells. "Three out of five SOX10 positive cases were SqCC and one case was an adenosquamous carcinoma." (PMID 30205833, 2018).
adrenal crisis (1 paper, 2022). "The rapid death of a subgroup of Sox10-CreERT2; Pik3caH1047R/+ mice after 4OH-TAM induction may also be due to adrenal crisis." (PMID 36353506, 2022).
ameloblastoma (1 paper, 2023). The most common odontogenic tumor, arising from the epithelial component of the embryonic tooth and usually affecting the molar-ramus region of the mandible or maxilla. "We identified LRP5, SLC6A3, and SOX10 as potentially important genes related to the cell proliferation and invasion of ameloblastomas through a large-scale gene expression analysis using a microarray approach, validating the expression results through immunohistochemical assays." (PMID 37628576, 2023). "In ameloblastoma, the overexpression of SOX10, LRP5, and SLC6A3 may possibly be related to increased cell proliferation, local invasion, and high recurrence rates; as such therapeutic alternatives such as parthenolide and vorinostat may be employed as inhibitors of these genes." (PMID 37628576, 2023).
angioleiomyoma (1 paper, 2025). A benign, slow-growing neoplasm that arises from the dermis or subcutaneous tissue. "Lack of reactivity to neural and histiocytic markers (e.g., S100, SOX10, CD68) helps distinguish angioleiomyomas from other spindle cell neoplasms." (PMID 40755624, 2025). "Markers for neural and histiocytic origin including S100, SOX10, and CD68 were negative, confirming the diagnosis of angioleiomyoma and ruling out peripheral nerve sheath tumors and fibrohistiocytic lesions." (PMID 40755624, 2025).
apocrine carcinomas (1 paper, 2024). "The importance of distinguishing apocrine differentiation is underscored by its potentially favorable prognosis in comparison to other TNBC subtypes.27, ‐29 In the 50 apocrine carcinomas included in this cohort, 92% demonstrated an AR positive, K5 negative or focal, SOX10 negative immunophenotype." (PMID 37306115, 2024).
Areflexia (1 paper, 2025). Absence of neurologic reflexes such as the knee-jerk reaction. "Additionally, it is worth noting that one patient with a MITF pathogenic variant exhibited complete vestibular loss (areflexia), demonstrating that severe vestibular involvement is not exclusive to WS cases with SOX10 pathogenic variants." (PMID 40868272, 2025).
Ataxia (1 paper, 2021). Ataxia refers to impaired coordination of voluntary muscle movement. "Sox10-ErbB2V664E mice with Dox feeding from P21 developed severe motor dysfunction, including ataxia and tremors, and died around P35." (PMID 34725188, 2021).
basal-like breast carcinoma (1 paper, 2022). "Reproductive disorder diseases, such as basal-like breast carcinoma (BLBC), is also linked with SOX10 gene mutations." (PMID 36496864, 2022).
brain inflammation (1 paper, 2023). "In view of the critical regulatory role of Sox10 in the proinflammatory phenotypic switching of VSMCs, and the association between Sox10 and brain inflammation in the clinical public database and bioinformatics analysis, we examined the expression of Sox10 in the brain of the Sm22α−/− mice." (PMID 37108281, 2023).
cellular schwannoma (1 paper, 2023). A morphologic variant of schwannoma characterized by hypercellularity, Antoni A pattern, and the absence of well-formed Verocay bodies. "The results imply that SOX10 expression is significantly more prevalent in cellular schwannomas, and its loss of expression is indicative of MPNST when compared to cellular schwannomas." (PMID 38132479, 2023).
Cognitive impairment (1 paper, 2023). Abnormal cognition is characterized by deficits in thinking, reasoning, or remembering. "In this study, we demonstrated that SM22α disruption promotes the expression of SRY-related HMG-box gene 10 (Sox10) in VSMCs, thereby aggravating the systemic vascular inflammatory response and involving brain tissues, leading to cognitive impairment." (PMID 37108281, 2023). "Finally, we confirmed that SM22α disruption promotes the expression of SRY-related HMG-box gene 10 (Sox10) in VSMCs, thereby aggravating the systemic vascular inflammatory response and ultimately leading to cognitive impairment in the brain." (PMID 37108281, 2023).
colitis (1 paper, 2023). Inflammation of the colon. "The authors showed that the Sox10-CreERT2 mediated knockout of the adenosine 2B receptor ADORA2B, in EGCs protected against DSS-induced colitis and normalized the mRNA expression and distribution of tight junction proteins." (PMID 37692784, 2023).